TRPV6 (transient receptor potential cation channel subfamily V member 6)
Diseases named in the same sentence as TRPV6 in open-access papers (continued):
Sharing a sentence is not in itself a finding about the gene and the disease.
tumor (continued). "In prostate cancer, TRPV6 mRNA levels are positively correlated to tumour progression and aggressiveness, pathological stages and extra-prostatic metastases, with poor prognosis." (PMID 37468801, 2023). "TRPV6 staining intensity rises by 67.9 ± 23.1% for tumor tissues and 18.3 ± 10.5% for peri-tumoral tissues between the early and late stages." (PMID 38136316, 2023). "TRPV6 overexpression was also present in breast cancer, where it correlated with invasive areas of the tumor." (PMID 38136316, 2023). "The staining intensity of TRPV6 was compared in tumor tissues against peri-tumoral tissues (as the control) and graded according to the scoring system ranging from 0 (no staining) to 3 (very intense staining)." (PMID 38136316, 2023). "Our results show that TRPV6 expression is upregulated in PDAC tumor tissues, but only in the later stages and especially in poorly differentiated ones." (PMID 38136316, 2023). "Taken together with the formation of osteoblastic lesions induced by TRPV6, the TRPV6 channels play essential roles in the modulation of tumor progression and osteoclast activation." (PMID 36071984, 2022). "There was also evidence that transient receptor potential cation channel subfamily V member 6 (TRPV6) has a major impact on cellular calcium influx, essential for the migration of tumour cells." (PMID 35163815, 2022). "In fact, by molecular imaging methods, the in vivo potential of soricidin-derived peptides in targeting TRPV6-rich tumours has been evaluated." (PMID 34065398, 2021). "For each model, after the acquisition of the MEMRI experiment, the animals were sacrificed and the tumour cells analyzed for assessing the level of expression of CaSR and TRPV6, respectively." (PMID 32931488, 2020). "In this set of experiments, both receptors, CaSR and TRPV6, demonstrated similar distribution at immunohistochemistry analysis across the different type of tumour lesions." (PMID 32931488, 2020). "Expression of TRPV6 mRNA and protein depend on the local environment of the cell and, in tumours, cell position." (PMID 31897233, 2020). "In these tumours the expression levels of CaSR and TRPV6 ranged between score 0 and 4 and both calcium receptors appear expressed at the same level in the same tumour." (PMID 32931488, 2020). "Further researches for cell cycle analysis, apoptosis analysis, invasion assays and tumor formation in vivo are required to explore the tumor-suppressive ability of TRPV6 and its related pathway." (PMID 26818094, 2016). "Generally, mRNA and proteins of TRPV5 and TRPV6 are up-regulated in tumour tissues and cell lines when compared with normal and correlate with tumour progression 8,31,33." (PMID 25164318, 2014). "Analysis of 40 tissue samples showed that TRPV6 transcripts occur in more than 90% of patients with extraprostatic prostatic adenocarcinoma indicating that patients with TRPV6 positive tumours have a bad prognosis." (PMID 19857260, 2009). "More than 90% of pT3b tumours express TRPV6 transcripts, whereas TRPV6 expression is only in 20% of pT2 tumours detectable." (PMID 19857260, 2009). "Upregulation of TRPV6 activity was also proposed to play a crucial role in tumor progression." (PMID 41198662, 2025). "Thus, mAb82 can be used to target TRPV6-expressing tumors in vivo reducing tumor burden and increasing animal survival." (PMID 38879621, 2024). "Thus, in the current work we demonstrate successful design, generation, and targeting of human TRPV6 channel in PCa using mAb82 leading to the cell death via apoptosis in vitro and tumor regression in vivo." (PMID 38879621, 2024). "Furthermore, we found that poorly differentiated tumor tissues express more TRPV6 than highly differentiated ones." (PMID 38136316, 2023). "This indicates that TRPV6 expression is elevated in highly proliferative PDAC tumor cells." (PMID 38136316, 2023).
tumor (continued). "Notably, the data indicate a direct correlation between TRPV6 expression levels, tumor stage, and grade, establishing a link between TRPV6 and PDAC proliferation in tissue samples." (PMID 38136316, 2023). "Furthermore, the inhibition of TRPV6 channels in an SKOV-3 xenograft model in mice led to reduced tumor formation." (PMID 38136316, 2023). "The mean tumor volume at 10 weeks is 525 ± 132 mm3 for Panc-1-mCherry cells, 410 ± 118 mm3 for Panc-1-shLuciferase, 194 ± 30 mm3 for Panc-1-shTRPV6 cells and 137 ± 55 mm3 for Panc-1-mCherry-TRPV6 cells." (PMID 38136316, 2023). "One possible explanation is that TRPV6 expression may affect other aspects of tumor biology, such as angiogenesis, inflammation, or immune response, which are not captured in the in vitro assays." (PMID 38136316, 2023). "So far, we have seen a correlation between TRPV6 staining and tumor aggressiveness in patient samples which we could, by and large, recapitulate in in vitro experiments." (PMID 38136316, 2023). "Our results also show that TRPV6 expression modulates tumor growth in vivo in a mouse model." (PMID 38136316, 2023). "However, the lack of further studies focusing on the effect of extracellular acid pH on TRPV6 activity makes a comprehensive understanding of the role of acid pHe on TRPV6 in the context of tumour acidosis difficult." (PMID 35806388, 2022). "TRPV6 has been studied as a tumour marker and target but its role in nociception and NP remains unknown." (PMID 34331199, 2021). "Moreover, by immunohistochemical analysis, it was found that TRPV6 is mainly localized in the cytoplasm in both tumor and normal tissue." (PMID 33178018, 2020). "Correlations of TRPV6 over-expression and Gleason scores extended to extra-prostatic extensions 42 and a role for TRPV6 in predicting prostate malignancies was suggested as TRPV6-positive tumours often invade extra-prostate tissues 90, 91 with a poor prognosis." (PMID 31897233, 2020). "Overall the incidence of TRPV6 gene amplification was 33 gene duplications in 4,517 tumours (0.7%) and thus, is not likely a common cause of TRPV6 expression changes." (PMID 31897233, 2020). "SNR and SE% (calculated as [(SNR-SNR0)/ SNR0]×100) for all tumour lesions respectively, of xenotransplant and pseudometastatic tumour animal model, before and 90 minutes after manganese administration and CaSR or TRPV6 expression levels evaluated by immunohistochemistry." (PMID 32931488, 2020). "At present, it is unclear whether the elevated TRPV6 expression promotes tumor growth or it is an adaptive response." (PMID 31526479, 2019). "Our findings suggested that TRPV6 might have tumor-suppressive ability and inhibit the progression of ESCC." (PMID 26818094, 2016). "Similarly, decreased TRPV6 levels were detected in androgen-insensitive tumours after androgen deprivation therapy." (PMID 25481381, 2014). "The link between tumour growth and protein overexpression of TRPV6 may involve the potentiation of calcium-dependent cell proliferation and the inhibition of apoptosis 12,30,31." (PMID 25164318, 2014). "The link between tumor growth and over-expression of TRPV6 may involve the potentiation of calcium-dependent cell proliferation and inhibition of apoptosis." (PMID 23554944, 2013). "Notably, TRPV6 expression correlated with tumor stage and grade, relating it to PDAC proliferation." (PMID 38136316, 2023). "In conclusion, we speculate that TRPV6 may have a tumor-suppressive ability." (PMID 36012311, 2022). "pH also regulates the activity of another component of the TRP vanilloid family, TRPV6, a highly Ca2+ selective channel (PCa/PNa~100) that is upregulated in different epithelial cancers, such as prostate, pancreatic, breast and ovarian cancer, in particular during early stages of tumour progression." (PMID 35806388, 2022). "Still, the exact role of TRPV6 in tumour progression and development remains unclear." (PMID 35163815, 2022).
tumor (continued). "TRPV6 inhibitors suppress tumor growth, but the molecular mechanism of inhibition remains unknown." (PMID 29941865, 2018). "Thus, in prostatic adenocarcinoma, TRPV1 and TRPV6 are overexpressed with respect to healthy prostatic tissues, and their expression levels correlate strictly with Gleason score, pathological stage, extraprostat extension and tumor grades." (PMID 22523714, 2012). "We also investigated the relationship between TRPV6 expression and cell proliferation in PDAC tumor tissues using the proliferation marker Ki-67." (PMID 38136316, 2023). "Specifically, polyamine synthesis inhibition decreased the expression of the TRPV6 and TRPP1 channels, as well as the Orai1 positive modulator SPCA2, probably contributing to decreased Ca2+ influx in DFMO-treated tumor cells." (PMID 36900391, 2023). "The results showed that TRPV2 and TRPV3 were upregulated in ccRCC tumor tissues, whereas TRPV5 and TRPV6 were downregulated in tumor tissues." (PMID 35558077, 2022). "We found significantly higher expression levels of TRPA1, TRPM8, and TCAF1/F2 in tumoral tissues compared to normal tissues, but lower expression levels of TRPV6, suggesting that TRP channels have either tumor-suppressive or oncogenic roles." (PMID 36012311, 2022). "The 50 most variable downregulated genes included the cytochrome P450 family 24 subfamily A member 1 (CYP24A1), the onco‐channel TRPV6, and DKK2 (i.e., a Wnt mediator of tumor immune evasion)." (PMID 35079680, 2022). "High expression of TRPM4 and TRPM7 was detected in primary tumor biopsies, while TRPV4, TRPC4, TRPC6 and especially TRPV6 expression was limited, while the expression of TRPC1 and TRPV2 are moderately expressed." (PMID 34936030, 2021). "Targeting TRPV6 with TRPV6-specific, antagonistic peptides reduced growth of SKOV-3 tumour xenografts in mice 100 further supporting this channel as a viable target." (PMID 31897233, 2020). "The PC3Mtrpv6-/- cell line lacking TRPV6 was grafted onto the Swiss nude mice and treated in the same way to show that the tumor growth was reduced exclusively by targeting TRPV6." (PMID 38879621, 2024). "Despite the role of TRPV6 in PCa cell survival and apoptotic resistance has been already established, no reliable tool to target TRPV6 channel in vivo and thus to reduce tumor burden is known to date." (PMID 38879621, 2024). "No study reported a link yet between the TRPV6 channel and tumor angiogenesis, thus constituting a new line of research." (PMID 37576552, 2023). "A study investigating mRNA expression levels of the TRP channels in human CRC tissue versus normal colon mucosa detected an increase in gene expression of TRPM8, TRPV6, and TRPV1 and a lower expression of TRPV4, TRPM4, TRPV3, TRPC6, and TRPV5 in the tumor tissues of CRC compared to normal tissues." (PMID 32182937, 2020). "In this latter study there was greater TRPV6 expression (3 - 4X) in smaller (≤2 cm) than in larger (>2 cm) Stage I breast tumours, but about the same in both size categories of Stage III tumours and showed particular concentration of the channel in invasive regions." (PMID 31897233, 2020). "The relative expression level of TRPV6 was significantly down-regulated in tumor tissues compared with paired adjacent nontumor tissues (P < 0.001)." (PMID 26818094, 2016). "In addition to their binding to the TRPV6 channel, per se, NMR evidence suggests that SOR peptides are stabilized by membrane environments found in tumor cells." (PMID 23554944, 2013). "The results indicate that the TRPV6 genotype is not correlated with an extraprostatic tumour growth." (PMID 19857260, 2009). "TRPV6 gene expression was higher in normal tissues vs. in PDAC tissues (p = 2.25 × 10−7), in normal tissues vs. metastatic tissues (p = 3.20 × 10−4, in tumor tissues vs. metastatic tissues (p = 1.79 × 10−8), and in normal vs. metastatic tissues." (PMID 36012311, 2022).
prostate (3 papers, 2020 to 2022). "Of four generated antibodies, only rabbit polyclonal anti-TRPV6 antibody rb79 produced a stable and clear staining of prostate cancerous epithelial cells." (PMID 36613866, 2022). "Different expression levels of both calcium receptors (ranging from 0 to 3 for CaSR and from 0 to 4 for TRPV6) was observed, in particular, in some of the prostatic lesions the expression levels of the two calcium receptors were different." (PMID 32931488, 2020).
skeletal dysplasia (3 papers, 2018 to 2021). Any Mendelian diseases that affects growth and development of the skeleton. "Recently, we reported a case of an infant with neonatal severe under-mineralizing skeletal dysplasia caused by mutations within both alleles of the TRPV6 gene." (PMID 34884497, 2021). "TRPV6 mutations have recently been associated with an antenatally severe under-mineralising skeletal dysplasia accompanied by postnatal biochemical abnormalities." (PMID 32228492, 2020). "Taken together, we demonstrate that the mutations in the TRPV6 gene of the affected child lead to reduced Ca2+ uptake in heterologous expression system, which may explain the skeletal dysplasia observed in the new born." (PMID 34884497, 2021). "Whereas, in this publication, we focus on the post-mortem findings of this case, which are the first in TRPV6-associated skeletal dysplasia, shedding new insight into the abnormal bone architecture of this condition and skeletal development in the perinatal period." (PMID 32228492, 2020). "Significant skeletal recovery occurs in the early weeks of postnatal life in TRPV6 skeletal dysplasia." (PMID 32228492, 2020). "This is the first post-mortem report in a patient with TRPV6 skeletal dysplasia." (PMID 32228492, 2020). "Until now, TRPV6 has not been linked with disorders of bone mineralization or skeletal dysplasia." (PMID 30144375, 2018).
infection (2 papers, 2018 to 2025). The state of being infected such as from the introduction of a foreign agent such as serum, vaccine, antigenic substance or organism. "Specifically, the addition of FUC caused a further reduction in mRNA expression levels of NHE2, TRPV6, APOA1, APOA4, APOB, APOC3, and ASS1 compared to PEDV infection alone, while FUC supplementation counteracts PEDV-induced ARG1 upregulation." (PMID 40218394, 2025).
cardiovascular diseases (1 paper, 2024). "However, limited research has focused on the impact of TRPV6 on inflammatory response and cell apoptosis in cardiovascular diseases." (PMID 39742020, 2024).
TRPV6 also shares sentences with these, for which no sentence is quoted: adenocarcinoma (3 papers); breast ductal adenocarcinoma (2); ovarian tumor (2); rickets (2); vitamin D deficiency (2); alopecia (1); Alzheimer disease (1); anemia (1); bladder cancers (1); cardiac hypertrophy (1); Dent disease (1); dry eye (1); endometriosis (1); head and neck carcinoma (1); Hypocalciuria (1); inflammation (1); injury (1); Lowe syndrome (1); lung adenocarcinoma (1); lymphoma (1); ovarian cystadenocarcinoma (1); pancreatic adenocarcinoma (1); preeclampsia (1); prostatic intraepithelial neoplasia (1); rectal tumor (1); renal carcinoma (1); Renal tubular dysfunctions (1); retinoblastoma (1); secondary hyperparathyroidism (1); skin cancer (1).
A further 2 diseases each share a sentence with TRPV6 in 1 paper.